IFNG (interferon gamma)
Diseases named in the same sentence as IFNG in open-access papers (continued):
Sharing a sentence is not in itself a finding about the gene and the disease.
tumor (continued). "As a consequence of this immune activation, the tumor microenvironment becomes enriched with pro-inflammatory cytokines, such as interleukin-2 (IL-2), interleukin-6 (IL-6), interferon gamma (IFN-γ), and tumor necrosis factor alpha (TNF-α)." (PMID 40807154, 2025). "PA-Vγ9Vδ2-T cells showed a significantly increase in killing tumor cells when IFNγ was neutralized in mice fed on the palm oil HFD." (PMID 40603316, 2025). "We calculated the correlation between HG-T, demographic variables (age and sex) and tumor variables (PD-L1 positivity; log10 TMB; and a composite score of either CD8+ T cell tumor infiltration > median, tumor IFNγ expression score > 0, or both)." (PMID 40473950, 2025). "It leads to interleukin-1β (IL-1β) secretion and activation of tumor antigen-specific, interferon γ (IFNγ)-producing CD8+ T cells." (PMID 41209313, 2025). "In this study, we demonstrate that IFNγ in the tumor microenvironment can potentiate TKI response, and that ablation of IFNγ receptor on HCC cells leads to TKI resistance in vivo." (PMID 40645933, 2025). "The integration of the observed associations with established tumor-based predictors, including tumor PD-L1 expression, TMB and IFNγ score, is of particular clinical importance." (PMID 40473950, 2025). "In parallel, ILC1s are being recognized for their capacity to mediate direct tumor cell killing via interferon-gamma (IFN-γ) production." (PMID 40963622, 2025). "IFNγ is a critical cytokine produced by T cells that plays a vital role in enhancing the immune response against tumors, promoting anti-tumor activity, and influencing other immune cells’ functions." (PMID 40386779, 2025). "The HSD group showed higher activity of NK cells and interferon gamma (IFNγ), which are important for the intratumor immune response, and had significantly less tumor progression and significantly higher survival than the LSD and ND groups." (PMID 39857680, 2025). "Our research demonstrated that IFNG facilitated tumor angiogenesis via HMGB1 pathways, mitigated by HMGB1 inhibition." (PMID 39945555, 2025). "Experimental evidence shows that STAT1 knockout in tumor cells blocks IFNγ‐induced SLC7A11 downregulation and significantly reduces RSL3‐triggered LPO and ferroptosis susceptibility." (PMID 40919133, 2025). "The most robust effort to date, an analysis of over 1,000 tumors across 10 tumor subtypes using CPTAC proteogenomics data, identified that mutations in Keap1 and NRF2 were associated with diminished IFNγ and CD8 T cells." (PMID 40946102, 2025). "In the tumor microenvironment, G-T cells engaged in stronger immune crosstalk with dendritic cells (DCs), upregulating interferon-gamma (IFN-γ) and interleukin-12 (IL-12) secretion and amplifying the anti-tumor immune response." (PMID 41355605, 2025). "Previous studies have indicated that the IFNγ produced by CD8+T cells appears to improve antitumor responses by enhancing tumor sensitivity to ferroptosis." (PMID 39820341, 2025). "Similar to αβ T cells, effector γδ T cells can exert a directly anti-tumor effect through producing various cytokines such as perforin, granzyme B and interferon gamma (IFN-γ)." (PMID 40483533, 2025). "Macrophages that deplete Irg1 are polarized towards a pro-inflammatory state after lipopolysaccharide (LPS) and IFNγ stimulation, leading to enhanced tumor suppression and increased survival." (PMID 40521193, 2025). "Tumor cell ferroptosis, a new CD8+ T cell-mediated tumor clearance mechanism, is associated with immune-activated CD8+ T cells and lipid peroxidation via IFNγ, making tumor cells more sensitive to ferroptosis." (PMID 40901678, 2025). "TNBCvax vaccination significantly increased CD8+ T cell infiltration and also upregulated the anti-tumor key effector molecules such as TNFα, IFNγ, and Granzyme B expression." (PMID 40969744, 2025).
tumor (continued). "Addition of IFNγ to coculture from day 0 induced MHCII expression in a proportion of PSCs similar to monoculture, suggesting prior exposure to tumor-derived signals suppresses IFNγ-mediated MHCII expression." (PMID 40215177, 2025). "In TNBC, high tsMHC-II expression correlates with more tumor-infiltrating lymphocytes (TILs) and activation of the interferon-gamma pathway." (PMID 40495188, 2025). "Once activated, CD8+ T cells will induce tumor cell killing and secretion of cytokines such as interferon γ (IFNγ) and tumor necrosis factor α." (PMID 41032705, 2025). "Interferon‐gamma (IFN‐γ) is a pro‐inflammatory cytokine that plays a crucial role in immune responses against infections, tumor immunity, and autoimmune regulation." (PMID 40196227, 2025). "In contrast, SFV/IFNγ is more effective in promoting inflammatory responses and inhibiting cell migration, making it suitable for regulating immune responses and limiting tumour metastasis." (PMID 40547518, 2025). "Of them, IFNB1 and IFNG, both belonging to the interferon family, play crucial roles in anti-tumor immunity." (PMID 40928500, 2025). "Conversely, in a model of passive immunotherapy (neu TAA-specific mAb injection), CD8+ T cells infiltrating the tumours were found to be exhausted (PD-1+) with poor IFNγ production, a phenomenon also captured through imaging." (PMID 40265075, 2025). "Three hours after injection, the number of trapped IFNγ-particles in the primary tumor and pulmonary metastases (●, ▲, a) was significantly higher than that in the surrounding muscles and lung tissue (■, ◆b)." (PMID 40244495, 2025). "Upon activation from tumor ligands, NK cells rapidly produce abundant IFNγ and TNFα in the presence of IL-12/IL-18 derived from activated tumor-resident macrophages and DCs." (PMID 40410571, 2025). "In mouse models, bystander IFNγ signaling has been observed in TAA− cells up to 800 μm away from the site of T‐cell mediated killing of a TAA+ tumor area." (PMID 40178291, 2025). "It has been shown that antigen-negative cells in tumors can be destroyed by T cells via bystander lysis, through secretion of cytotoxic cytokines (eg, interferon gamma) as long as antigen-positive tumor cells are present." (PMID 40613043, 2025). "This study developed a machine learning model that leverages pathomics to forecast IFNG expression based on histopathological images while thoroughly examining the tumor immune microenvironment in HNSCC." (PMID 41368643, 2025). "The results were confirmed in mice with this tumor, where IFNγ reduced tumor size and increased tumor killing activity induced by PD-1 antibody, accompanied by increased NETs formation and cell apoptosis." (PMID 41019086, 2025). "NKG2D binding to its ligands on tumor cells activates NK cells, enhances cytotoxicity, and stimulates IFNγ production, facilitating a robust anticancer immune response." (PMID 40013140, 2025). "Using the Tgfbr1/Pten double KO mouse model, the application of an αTim- 3 antibody reduced Treg count and restored IFNγ production haltering tumor growth." (PMID 40666515, 2025). "Our findings demonstrate that SFV vectors, particularly those engineered to deliver TNFα or IFNγ, can reprogramme macrophages towards an anti-tumour phenotype, with substantial implications for cancer immunotherapy." (PMID 40547518, 2025). "After 48 hours, PBMCs produced significantly higher levels of IFNγ and Granzyme B when co-cultured with tumor cells treated with MYC inhibitors." (PMID 40552293, 2025). "As a result, triple therapy also increased the IFNγ+ CD8+ T-cell frequency in the B16F10 tumor model." (PMID 41291775, 2025). "We have recently identified the interferon-stimulated noncoding RNA 1 (INCR1) as a novel lncRNA transcribed from the PD-L1 locus and showed that INCR1 is highly inducible in tumor cells stimulated with IFNγ." (PMID 40035950, 2025).
tumor (continued). "A recent article reported that interferon gamma (IFN-γ) significantly induced PD-L1 expression in tumor cells responding to cancer progression." (PMID 41008336, 2025). "In contrast, fewer immunosuppressive Treg cells were distributed in the tumor after treatment with Nano-IFNγ/Zole." (PMID 39776793, 2025). "In a groundbreaking study aimed at enhancing the efficacy of tumor immunotherapy, researchers focused on inhibiting the interferon gamma (IFN-γ) pathway in tumor cells." (PMID 41155765, 2025). "This predictive relationship is primarily due to its upregulation by interferon-gamma, which is released by immune cells (mainly T lymphocytes and natural killer cells) in proximity to tumor cells, driving an immune resistance mechanism." (PMID 40649844, 2025). "Natural killer cells and CTLs induce tumor cell death by secreting pro-inflammatory cytokines such as interferon-gamma (IFN-γ), tumor necrosis factor-alpha (TNF-α), and cytotoxic mediators such as granzyme and perforin." (PMID 41011224, 2025). "Newly-infiltrating TAMs were most affected by PD-L1 blockade, which attenuated the rapid loss of inflammatory gene expression upon monocyte entry into the tumour and established self-potentiating IFNγ-driven responses between TAMs and CD4+ T cells." (PMID 40523200, 2025). "More importantly, PTSO significantly increased the frequency of cytotoxic CD3+CD8+ T (Tc) cells, accompanied by a notable rise in IFNG-producing Tc1 cells (CD8+IFNG+), indicating a skewing towards an effector anti-tumor phenotype." (PMID 41010517, 2025). "It has been reported in literature that increased levels of PD-L1 expressed on the surface of tumor cells, in specimens that are freshly isolated from patients with cancer, were found to be induced by IFNγ." (PMID 39929828, 2025). "Immune checkpoint blockade has been shown to upregulate IFNγ, which in turn facilitates the clearance of tumor cells across various cancers." (PMID 39788975, 2025). "For example, IFNγ released by CD8+ T cells suppresses SLC7A11 expression in tumor cells, linking immune surveillance to ferroptotic clearance—a mechanism exploited in ICI therapies." (PMID 40919133, 2025). "This mineralized nano-IFNγ was dispersed in alginate gel and injected into the peripheral tumor during the final stage of RFA surgery." (PMID 39776793, 2025). "Before we investigated ARID1A loss and IFNγ signaling cytokines, we wanted to explore previous findings connecting MYCN amplification with the cold tumor phenotype." (PMID 40082458, 2025). "In this study, we demonstrate a novel mechanism in which IFNγ-insensitive tumours trigger remodelling of the tumour microenvironment through accumulation of IFNγ which leads to effective tumour control." (PMID 39746898, 2025). "In line with the previous co-culture experiments, we evaluated daily perfused media for IFNγ levels, serving as an indicator of an immune-mediated anti-tumor response." (PMID 40873566, 2025). "In the context of the anti-tumor immune response unleashed by anti-PD-1/PD-L1-based immunotherapy, interferon-gamma (IFN-γ) plays a major role." (PMID 40554927, 2025). "IFNα and IFNβ directly act on host hematopoietic cells, resulting in tumor inhibition, whereas IFNγ promotes tumor recognition by upregulating the MHC class I pathway, leading to enhanced T cell activation." (PMID 39857692, 2025). "Our finding is consistent with previous studies, which have shown that IFNG can augment the immune response against tumor cells by enhancing antigen presentation and promoting T-cell activation." (PMID 41368643, 2025). "Systemic administration of these nanohybridsfacilitates precise tumor targeting, induces antitumor cytokines suchas IFNγ, and suppresses immunosuppressive cytokine TGF-β,reshaping the TME." (PMID 40392526, 2025).
tumor (continued). "Interferon‐gamma (IFN‐γ) is a critical cytokine in tumour immunology, playing a dual role in both promoting anti‐tumour immunity and, paradoxically, contributing to tumour progression under certain conditions." (PMID 40165405, 2025). "IFNγ production by natural killers is triggered by their interaction with target cells (tumor, virus-infected)." (PMID 40806737, 2025). "Across both tumour types, CD8-monocyte gene signature expression coincided spatially with hallmark IFNγ response signatures and endothelial cell markers." (PMID 39746898, 2025). "These TILs were associated with the generation of pro-inflammatory cytokines, such as interleukin-2 (IL-2), tumor necrosis factor-α (TNF-α), and interferon-gamma (IFN-γ), suggesting metformin’s effect for activating anti-tumor immune responses." (PMID 40005128, 2025). "For example, the secretion of IFNγ at the tumor‐border across all donors after treatment with anti‐CD3/CD28 ranged from 440 to 60,000 pg/mL." (PMID 40952312, 2025). "HCC has been reported as an inflammation-suppressive cancer where Th17 cells curb tumor growth by secreting IFNG, counteracting the immunosuppressive role of Tregs." (PMID 40436857, 2025). "After this repolarization of TAMs in the tumor microenvironment, M1 macrophages would directly kill tumor cells by secreting interferon gamma (IFN-γ) and tumor necrosis factor alpha (TNF-α) etc." (PMID 39839492, 2025). "In particular, the activation of NLRP3 in dendritic cells (DCs) showed an anti-tumor activity via IL-1β/Th1/IFNγ." (PMID 39857785, 2025). "On d14 of our T cell expansion protocol, we restimulated this patient’s T cell cultures with matched tumor cells and observed increased IFNγ release and tumor cell killing in LTA compared with placebo-expanded cultures." (PMID 41042672, 2025). "While CTLs directly destroy tumor cells, Th1 cells enhance anti-tumor immune responses by secreting proinflammatory cytokines such as interferon gamma (IFN-γ)." (PMID 40806346, 2025). "They mediate direct tumor cell killing through the secretion of perforin, granzymes, and pro-inflammatory cytokines such as interleukin (IL)-2, IL-12, and interferon-gamma (IFN-γ)." (PMID 40872551, 2025). "In contrast, more CD163+ and CD206+ M2 macrophages were recruited and distributed continuously in the residual tumor tissue and the addition of Nano-IFNγ/Zole significantly reversed this tendency." (PMID 39776793, 2025). "In the tumor‐T co‐culture assay, treatment with AhR siRNA resulted in further increase in IFNγ levels of T cells activated by tumor cells in the absence or presence of I3A stimulation." (PMID 40583248, 2025). "Cytotoxic CD8+ T cells induce ferroptosis in tumor cells by secreting interferon-gamma (IFNγ), which inhibits xCT anti-porter, leading to GSH depletion and lipid peroxidation." (PMID 40075648, 2025). "We treated MC38 tumor-bearing mice with irrelevant IgGs or an IFNγ neutralizing antibody and interrogated the distribution of Mono_1-like, Macro_1,3-like, and Macro_2,4,5,6-like cells by flow cytometry." (PMID 40475851, 2025). "In a recent study, a comparable CRISPRa technique was utilized to simultaneously activate multiple endogenous genes such as Cd70, Cd80, Cd86, Ifnα4, Ifnβ1, and Ifnγ, triggering anti-tumor adaptive immune clearance of tumor cells in a mouse model." (PMID 41283440, 2025). "Our research has focused on the tumor microenvironment conditions with the cytokine IFNγ, secreted by activated immune cells such as T cells and natural killer (NK) cells." (PMID 39258533, 2025). "CD3+ T cells recognize tumor-associated antigens on the surface of tumor cells, release cytokines (such as interferon-gamma), and directly kill tumor cells, thereby inhibiting tumor growth." (PMID 41001043, 2025). "Tumor cells upregulate the PD-L1 receptor through an elaborate route that includes DNA damage signaling, IFNγ signaling, and the EGFR pathway." (PMID 39851804, 2025).
tumor (continued). "Given the importance of IFNγ for controlling IFNγRKO tumours and remodelling of the myeloid landscape, we sought to identify the cellular source of IFNγ in WT and IFNγRKO tumours." (PMID 39746898, 2025). "Single-cell RNA sequencing (scRNA-seq) analysis revealed interferon-γ (IFNγ)-dependent immunostimulatory programming of the tumor microenvironment in DKO mice." (PMID 40475851, 2025). "By secreting interferon-gamma (IFN-γ), cytotoxic T-cells not only destroy tumor cells but also inhibit angiogenesis." (PMID 40230883, 2025). "IFNG emerges as a potential prognostic biomarker and therapeutic target, influencing both the tumor microenvironment and angiogenesis." (PMID 39945555, 2025). "This design led to increased IFNγ production, improved T cell proliferation, and recursive tumor cell killing in vitro." (PMID 40969762, 2025). "This signature is enriched for genes involved in MHC class I/II antigen presentation, interferon-gamma signaling, antigen processing, and complement cascade, collectively representing the transcriptional hallmarks of a T-cell inflamed tumor microenvironment." (PMID 41514531, 2025). "Tumor cells can also develop resistance by downregulating antigen expression or disrupting interferon-gamma (IFN-γ) signaling pathways." (PMID 40508202, 2025). "CAR T cell treatment was also accompanied with the strongest interferon (IFN)γ release within the tumor two days after treatment whereas IFNγ concentrations within the plasma remained below detection limit." (PMID 39889712, 2025). "Then a zoledronate-mineralized nanoparticle loaded with IFNγ (Nano-IFNγ/Zole) was designed and its tumor suppressive efficacy was evaluated." (PMID 39776793, 2025). "Metabolic reprogramming of NK cells significantly inhibits their normal anti-tumor function, resulting in the inability to secrete cytokines such as IFNγ as well as IL-2 normally." (PMID 40356913, 2025). "SCFAs have bifunctional utility: reducing the secretion of IL-10, an anti-inflammatory cytokine that promotes tumor cell proliferation via immunosuppression, while also increasing NK extracellular vesicle secretion of IFNγ that aids in tumor-killing." (PMID 40422211, 2025). "We have recently found that peritumoral administration of a regulatable IL12 gene therapy in subjects with recurrent GBM showed increased inflammatory GBM infiltrates, including increased numbers of CD8 + T cells and elevated levels of tumor IFNγ." (PMID 40035950, 2025). "The macrophages are associated with histologically evident phagocytic clearance of tumor cells which is quite expected due to the concerted action of upregulated immune activating effects of IFNγ and TNFα." (PMID 40560386, 2025). "IFNγ also promoted NK cell-mediated pyroptosis in target tumor cells by upregulating GSDMB expression." (PMID 40645933, 2025). "Tumor CTLA4 expression was positively correlated with the prevalence of TILs and TLS in tumors and with a wide range of immune-related gene expression signatures, including the cytotoxicity, interferon gamma, and tumor inflammation signatures." (PMID 40523912, 2025). "IFNγ production peaked ~10 days post-tumour induction and was overtaken by CD8+ T cells during latter stages of tumour progression (i.e. days 14–16), regardless of the tumour type." (PMID 39746898, 2025). "The primary goal of this design was to achieve long-term release of IFNγ in tumor tissues through protein granulation and gel encapsulation, thereby fulfilling the continuous reversal of the suppressive TIME." (PMID 39776793, 2025). "This approach significantly promotes CD8+ T cell infiltration and augments functional activity (like granzyme B and IFNγ), ultimately resulting in tumor regression and prolonged survival." (PMID 40861443, 2025). "Previously, it has been reported that activated T cell-derived IFNγ triggers ferroptosis, thereby contributing to the anti-tumor efficacy of immunotherapy." (PMID 41339438, 2025).